ARID1A (AT-rich interaction domain 1A)
Diseases named in the same sentence as ARID1A in open-access papers (continued):
Sharing a sentence is not in itself a finding about the gene and the disease.
uterine carcinosarcoma (5 papers, 2015 to 2024). A usually aggressive malignant neoplasm arising from the uterine corpus and less often the cervix.
uterine corpus endometrial carcinoma (5 papers, 2014 to 2021). A endometrial carcinoma (disease) that involves the body of uterus. "ARID1A mutations also correlated with better survival in uterine corpus endometrial carcinoma." (PMID 32967217, 2020).
uterine tumors (5 papers, 2012 to 2020). "Mutations in CTNNB1, PTEN, and ARID1A were recurrent among the six uterine tumors (50%, 50%, and 33%, respectively), which is also consistent with previous reports from all-age-group uterine tumors." (PMID 29464067, 2018). "Similar to previous studies it could be determined that ARID1A loss in ovarian and uterine tumors is a predictor for poor survival." (PMID 29451900, 2018). "Simultaneous deletions of Arid1a and Pten in iPAD mice resulted in grossly visible uterine tumors 6 weeks after doxycycline-induced knockout, while iAD mice or iPD mice (with single gene knocked out) did not present any gross tumors at the same time." (PMID 32483112, 2020).
Cirrhosis (4 papers, 2020 to 2024). A chronic disorder of the liver in which liver tissue becomes scarred and is partially replaced by regenerative nodules and fibrotic tissue resulting in loss of liver function. "Further analysis revealed that the ARID1A deficient group was associated with cirrhosis, which is the main risk factor for HCC initiation." (PMID 38166741, 2024). "The present study adds the current evidence in the field by investigating the impact of MYC amplification and ARID1A on prognosis in a population of patients with a low prevalence of cirrhosis and viral hepatitis undergoing liver resection for HCC." (PMID 38536546, 2024).
colon adenocarcinoma (4 papers, 2019 to 2024). "In colon adenocarcinoma (COAD), the low expression of ARID1A was reported but the molecular reason is unclear." (PMID 34414106, 2021).
colorectal adenocarcinoma (4 papers, 2019 to 2025). The most common type of colorectal carcinoma. "Indeed, examination of the TCGA PanCancer Atlas colorectal adenocarcinoma cohort revealed that KRAS mutations were mutually exclusive with ARID1A mutations with only 16 out 526 patients harboring mutations in both genes." (PMID 31217031, 2019). "It has also been shown that the biallelic (ARID1A−/−) deletion of ARID1A alone led to the formation of invasive colorectal adenocarcinomas in mice." (PMID 35611248, 2022). "Mutual exclusivity of ARID1A and KRAS (all and specifically at residues G12 and G13) mutations in the colorectal adenocarcinoma patient cohort from the TCGA PanCancer Atlas (b)." (PMID 31217031, 2019). "A tumor suppressor role of ARID1A has been established in a number of tumor types including CRC where the genetic inactivation of Arid1a alone led to the formation of invasive colorectal adenocarcinomas in mice." (PMID 31217031, 2019).
cutaneous melanoma (4 papers, 2022 to 2024). A primary melanoma arising from atypical melanocytes in the skin. "ARID2 mutations were more prevalent in cutaneous melanoma compared to ARID1A (11.0%: n = 451 vs 2.8%: n = 113), with concurrent ARID1A/ARID2 mutation in 1.1% (n = 46) of samples." (PMID 38341515, 2024). "The frequency of ARID1B mutations in cutaneous melanoma approaches that of ARID1A." (PMID 35323214, 2022). "ARID1A mutations primarily occur in cutaneous melanomas with a UV-signature high mutation burden." (PMID 35565222, 2022). "Interestingly, in our cohort ARID1A mutations appeared almost exclusively in cutaneous melanoma." (PMID 35565222, 2022). "Cutaneous melanoma ranks 7 among 32 different human cancers in the observed frequency of genetic alterations in ARID1A." (PMID 35323214, 2022).
diabetes mellitus (4 papers, 2019 to 2025). A metabolic disorder characterized by abnormally high blood sugar levels due to diminished production of insulin or insulin resistance/desensitization. "Previously, we generated genetically engineered mice with specific depletion of Arid1a gene in the pancreas and found that depletion of Arid1a at early developmental stage induced metabolic disturbance and diabetes mellitus." (PMID 40621620, 2025). "Previous work showed that depletion of Arid1a at early developmental stages induces metabolic disturbance and diabetes mellitus in mice." (PMID 40621620, 2025). "Our results demonstrated that depletion of Arid1a at early developmental stage impaired islet formation and decreased insulin secretion, which led to metabolic disturbance and diabetes mellitus." (PMID 40621620, 2025). "Whereas genes with decreased expression (ARID1A KO vs WT) were relevant to cancer pathways, including cell adhesion molecules, Type 1 Diabetes Mellitus, toxoplasmosis." (PMID 36420658, 2022).
Endometrioid Endometrial Carcinoma (4 papers, 2016 to 2023). "25–30% of the endometrial MLA cases harbor additional mutational events within the PTEN-, CTNNB1-, and ARID1A-genes which are also common mutational alterations in endometrioid endometrial carcinomas." (PMID 37668797, 2023). "This indicates that the ARID1A/ß-Catenin pathway connection might play a role in tumor progression in endometrioid endometrial carcinoma." (PMID 29451900, 2018).
esophageal adenocarcinoma (4 papers, 2016 to 2023). A malignant tumor with glandular differentiation arising predominantly from Barrett mucosa in the lower third of the esophagus. "Recently, ARID1A loss was detected in 10% of the 120 oesophageal adenocarcinomas examined in a work using a similar methodology." (PMID 31906887, 2020). "In the few studies that exist on oesophageal adenocarcinoma on this subject, individual components (ARID1A loss) of the SWI/SNF complex were analysed." (PMID 31906887, 2020). "ARID1A, a member of the chromatin remodeling SWI/SNF complex, is frequently lost in many cancer types, including esophageal adenocarcinoma (EAC)." (PMID 38001638, 2023). "During esophageal adenocarcinoma (EAC) development, somatic mutations of ARID1A and SMARCA4 are already present in benign metaplastic never-dysplastic Barrett's esophagus (NDBE)." (PMID 26812616, 2016).
Ewing sarcoma (4 papers, 2021 to 2025). A small round cell tumor that lacks morphologic, immunohistochemical, and electron microscopic evidence of neuroectodermal differentiation. "While the idea of EWS-FLI1 influencing alternative splicing was expressed almost two decades ago, the only functional relevance of such a function for the Ewing sarcoma oncogenic process was a splicing regulation of the ARID1A gene." (PMID 34009296, 2021).
head and neck squamous cell carcinoma (4 papers, 2016 to 2024). A squamous cell carcinoma that arises from any of the following anatomic sites: lip and oral cavity, nasal cavity, paranasal sinuses, pharynx, larynx, and salivary glands. "ARID1A mutations have been described as potential predictors of immune checkpoint inhibitor efficacy in head and neck squamous cell carcinoma." (PMID 36362284, 2022).
inflammatory bowel disease (4 papers, 2020 to 2025). A spectrum of small and large bowel inflammatory diseases of unknown etiology. "The presence and selection of large ARID1A mutant clones identified in the context of inflammatory bowel disease support such an interpretation." (PMID 39920335, 2025). "Although today’s study about ARID1A mostly concerns malignant tumors, evidence of its role in autoimmune diseases like inflammatory bowel disease has been described recently." (PMID 36969183, 2023).
metastatic cancer (4 papers, 2017 to 2023). A carcinoma which has spread from the original site of growth to another anatomic site.
thyroid cancer (4 papers, 2014 to 2025). "In vitro cell experiments demonstrated the promising modulation of thyroid cancer biomarker genes S100A6 and ARID1A by HA/CMCS-CP1@paclitaxel." (PMID 38844812, 2024).
viral infection (4 papers, 2020 to 2025). "Myeloid cell-specific deficiency of Arid1a rendered mice more susceptible to viral infection, accompanied with less IFN-I production." (PMID 34315861, 2021). "However, the expression of TNF-α and IL-6 in Arid1a-deficient BMDMs was comparable with that in control BMDMs upon virus infection." (PMID 34315861, 2021). "PBRM1 is a chromatin modulator of the SWI/SNF chromatin remodeling complex, which includes SMARCA4, SMARCB1, SMARCC1, ARID1A, DPF2, and SMARCE1, also implicated in ACE2 expression regulation and, thus, in host cell susceptibility to viral infection." (PMID 40378209, 2025). "Despite of the unchanged expression during the acute virus infection, we are curious about the function of ARID1A in antiviral immune response, considering its high abundance in immune-related cells." (PMID 34315861, 2021). "More studies are further needed to explore the expression pattern and roles of ARID1A protein in infectious diseases and virus infection-related cancers." (PMID 34315861, 2021). "The characteristics of downregulated genes in Arid1a cKO RGCs were related to viral infection, cell adhesion, and immune response, etc.." (PMID 32670021, 2020). "Thus, our results demonstrated ARID1A protects mice from virus infection by selectively promoting IFN-I production." (PMID 34315861, 2021). "On the one side, we found ARID1A interacts with IRF3, a crucial transcription factor that regulates the production of IFN-I in response to virus infection." (PMID 34315861, 2021). "Here we show that ARID1A is recruited by IRF3 to the promoter regions of Ifn-I, where it binds histone methyltransferase NSD2 to increase chromatin accessibility and promote IFN-I production in response to virus infection." (PMID 34315861, 2021). "Therefore, we demonstrated the interplay among the nuclear proteins including chromotin remodeler ARID1A, transcriptional factor IRF3, and histone modification protein NSD2 at the Ifn-I promoter regions which jointly regulate the production of IFN-I in innate immune cells upon virus infection." (PMID 34315861, 2021). "Here, we reported that epigenetic remodeler ARID1A, a critical component of the mSWI/SNF complex, could bind IRF3 and then was recruited to the Ifn-I promoter by IRF3, thus selectively promoting IFN-I but not TNF-α, IL-6 production in macrophages upon viral infection." (PMID 34315861, 2021).
acute promyelocytic leukemia (3 papers, 2019 to 2023). An aggressive form of acute myeloid leukemia (AML), characterized by arrest of leukocyte differentiation at the promyelocyte stage, due to a specific chromosomal translocation t(15;17) in myeloid cells. "Amongst hematological diseases, ARID1A is mutated in acute promyelocytic leukemia (APL) and several lymphoid malignancies." (PMID 30858552, 2019). "We identified a high frequency of ARID1A mutations, suggesting the involvement of the SWI/SNF chromatin remodeling complexes in the clinical presentation, acute promyelocytic leukemia‐like morphology and all‐trans retinoic acid/arsenic trioxide treatment resistance of ZBTB16‐RARA rearranged AMLs." (PMID 34042280, 2021).
bowel cancer (3 papers, 2021 to 2022).
Burkitt lymphoma (3 papers, 2015 to 2023). A rare form of malignant mature B-cell non-Hodgkin lymphoma. "In contrast to SMARCA2/4 and ARID1A/1B/2 genes, BCL7A seems to be specifically mutated in lymphomas that are either derived from or phenotypically similar to germinal center B cells, such as germinal center B cell-like (GCB) DLBCL, FL, Burkitt lymphoma (BL), and MM." (PMID 36810086, 2023).
choriocarcinoma (3 papers, 2020 to 2024). An aggressive malignant tumor arising from trophoblastic cells. "We found that overexpression of ARID1A suppresses choriocarcinoma cell migration and invasion, whereas inhibition of ARID1A promotes migration and invasion in choriocarcinoma cells, suggesting the tumor-suppressor function of ARID1A in choriocarcinoma progression." (PMID 34671561, 2021). "ARID1A is also involved in the development of choriocarcinoma, where its overexpression of ARID1A suppresses migration and invasion of choriocarcinoma cells, while its inhibition promotes migration and invasion, suggesting a tumor-suppressor role of ARID1A in choriocarcinoma progression." (PMID 38893181, 2024). "ARID1A expression was detected in type II GCT tissues (GCNIS, seminomas, ECs, teratomas) and cell lines (TCam-2 (seminoma), 2102EP, NCCIT (ECs), JAR (choriocarcinoma)), while ARID1B expression was expressed considerably weaker." (PMID 32272809, 2020).
endometrial adenocarcinomas (3 papers, 2016 to 2021). "ARID1A mutations have been shown to be associated with more aggressive endometrial adenocarcinomas." (PMID 28027320, 2016).
epithelioid sarcoma (3 papers, 2021 to 2022). An aggressive malignant neoplasm of uncertain differentiation, characterized by the presence of epithelioid cells forming nodular patterns. "In particular, the SWI/SNF subunit SMARCB1 has been approved as an effective marker of metastatic or locally advanced epithelioid sarcoma sensitivity to tazemetostat, while SMARCA2, SMARCA4, ARID1A, and PBRM1 are potential marker candidates." (PMID 34202528, 2021).
hepatoblastoma (3 papers, 2020 to 2022). Hepatoblastoma (HB) is a malignant hepatic tumor and is the most common pediatric liver cancer. "Moreover, a patient carrying an ARID1A pathogenic variant with hepatoblastoma was described previously in the literature." (PMID 34706719, 2021).
Hydrocephalus (3 papers, 2023). Hydrocephalus is an active distension of the ventricular system of the brain resulting from inadequate passage of CSF from its point of production within the cerebral ventricles to its point of absorption into the systemic circulation. "Shared abnormalities were growth delay, which has been observed especially in SMARCB1 pathogenic variants, and hydrocephalus, which has only recently been described as a common prenatal characteristic in ARID1A pathogenic variants (but not in SMARCB1 variants)." (PMID 37219662, 2023).
Infertility (3 papers, 2015 to 2022). "Since PGRCre mice show Cre recombinase activity in the pituitary, ovary, uterus and mammary glands, these mice may have infertility due to a defect of Arid1a in any of these tissues." (PMID 26378916, 2015). "To test this hypothesis, we generated uterine-specific Arid1a knock-out mice, which were infertile due to defective implantation and decidualization." (PMID 26378916, 2015). "However, the roles of ARID1A in infertility and endometrial function have not been studied." (PMID 26378916, 2015). "ARID1A, a SWItch/sucrose non-fermentable (SWI/SNF) chromatin remodeling complex protein, was recently found to be critical for endometrial function during early pregnancy after conditional deletion in the mouse uterus resulted in infertility due to implantation and decidualization defects." (PMID 31387263, 2019).
liver cirrhosis (3 papers, 2015 to 2024). "All clinical factors significantly related to the loss of ARID1A expression, were within small duct type of ICCs, such as decreased ALT, AST, lower incidence of liver cirrhosis and earlier TNM stage." (PMID 32293336, 2020). "Five patients had liver diseases (polycystic liver disease, liver fibrosis, liver cirrhosis, or chronic hepatitis B) with an average of 97 small somatic variants, including nonsilent variants in ARID1A, CSMD3, and KEAP1 and one copy gain of PBX1." (PMID 38877653, 2024).
Lynch syndrome (3 papers, 2021 to 2023). An autosomal dominant hereditary neoplastic syndrome characterized by the development of colorectal carcinoma and a high risk of developing endometrial carcinoma, gastric carcinoma, ovarian carcinoma, renal pelvis carcinoma, and small intestinal carcinoma. "In support of this, a complete pathologic response after two months of combined mFOLFOX6 with pembrolizumab therapy was recently reported in a Lynch syndrome patient suffering from an ARID1A mutated and tumor mutational burden (TMB) high dMMR CRC." (PMID 34206051, 2021). "By comparison, MMR defects due to germline variations (i.e., Lynch syndrome) appear to occur mainly in ARID1A-preserving cases." (PMID 35421925, 2022). "It is worth noting that the MMR defect pattern that suggests Lynch syndrome can also occur in tumors with ARID1A deletion." (PMID 35421925, 2022).
malignant rhabdoid tumors (3 papers, 2020 to 2022). "Based upon the combination of morphologic, immunohistochemical, and molecular features, a diagnosis of ARID1A deficient undifferentiated spindle cell and rhabdoid sarcoma of the prostate was rendered." (PMID 35125107, 2022). "We report an ARID1A deficient undifferentiated spindle cell and rhabdoid sarcoma of the prostate, adding to the growing spectrum of SWI/SNF driven undifferentiated sarcoma." (PMID 35125107, 2022).
microcephaly (3 papers, 2021 to 2025). A congenital or acquired developmental disorder in which the circumference of the head is smaller than normal for the person's age and sex. "Although Arid1a mutations are closely related to mental retardation and microcephaly, the function of Arid1a in brain development and its underlying mechanisms still remain elusive." (PMID 34562292, 2021). "Duplication of ARID1A (also known as BAF250A), a core subunit of the BAF complex, has been associated with microcephaly." (PMID 41283518, 2025). "Clinical studies have found that ARID1A (BAF250a) is the most frequently mutated SWI/SNF gene and its mutations lead to mental retardation and microcephaly." (PMID 34562292, 2021). "Conversely, haploinsufficiency of ARID1B (also known as BAF250B), a mutually exclusive paralog of ARID1A, similarly results in microcephaly, implying antagonistic roles in NSPC proliferation—with ARID1A-BAF functioning as a repressor and ARID1B-BAF as an activator." (PMID 41283518, 2025).